IDH1 (isocitrate dehydrogenase (NADP(+)) 1)
Diseases named in the same sentence as IDH1 in open-access papers (continued):
Sharing a sentence is not in itself a finding about the gene and the disease.
acute myeloid leukemia (continued). "IDH1 and IDH2 mutations (IDH1/2Mut) are recognized as recurrent genetic alterations in acute myeloid leukemia (AML) and associated with both clinical impact and therapeutic opportunity due to the recent development of specific IDH1/2Mut inhibitors." (PMID 33941203, 2021). "Mutations in isocitrate dehydrogenase 1 and 2 (IDH1/2) genes occur in about 20% patients with acute myeloid leukemia (AML), leading to DNA hypermethylation and epigenetic deregulation." (PMID 33976256, 2021). "Genome-wide mutation analyses and high-throughput deep sequencing have identified that 70% of grade II-III gliomas and secondary glioblastomas, as well as 10% of acute myeloid leukemia (AML), have mutations in IDH1 or IDH2." (PMID 32764295, 2020). "Acute myeloid leukemia (AML) frequently harbors mutations in isocitrate 1 (IDH1) and 2 (IDH2) genes, leading to the formation of the oncometabolite (2R)-hydroxyglutaric acid (2R-HG) with epigenetic consequences for AML proliferation and differentiation." (PMID 33019704, 2020). "IDH1 mutations were first described in central tumors and acute myeloid leukemia (AML), and then in the number of hematopoietic neoplasms (myelodysplastic syndrome, T cell lymphoma) and sarcomas (chondrosarcoma, central chordoma, periosteal chondroma)." (PMID 30708988, 2019). "Targeted NGS analysis performed at diagnosis and focused on acute myeloid leukemia driver genes is helpful since the presence of pathogenic mutants (IDH1 p.Arg132His, SRSF2 p.Pro95Thr, WT1 p.Cys393Ter in this study) could represent additional risk factors or opportunities for targeted therapy." (PMID 30848074, 2019). "Promisingly, ivosidenib (AG-120) has been approved by FDA as first-line treatment for acute myeloid leukemia (AML) with IDH1 mutation after a positive clinical trial (NCT02074839), further indicating the therapeutic potential of targeting this alteration." (PMID 31450721, 2019). "The somatic mutations in IDH1 were observed in patients with acute myeloid leukemia (AML) and are possibly associated with a higher proportion of Treg cells in bone marrow." (PMID 31398943, 2019). "However, when IDH1 is mutated in gliomas and acute myeloid leukemias (AML), R2HG is produced." (PMID 29619217, 2018). "IDH1/2 mutations have consequently been detected in acute myeloid leukemia (AML) and myelodysplastic disorders, but rarely in thyroid, prostate, B cell lymphoma, and colorectal carcinomas." (PMID 26161668, 2015). "Ivosidenib is a mutant IDH1 (mIDH1) inhibitor that demonstrated clinical benefit in combination with azacitidine for treatment of mIDH1 acute myeloid leukemia (AML) in the phase 3 AGILE trial." (PMID 41774395, 2026). "Insights from acute myeloid leukemia suggest that receptor tyrosine kinase mutations, secondary IDH mutations, and isoform switching (e.g., IDH1 to IDH2) can mediate resistance." (PMID 41008893, 2025). "Mutant IDH1 and IDH2 generate 2-hydroxyglutarate, disrupt TET2 function, enforce DNA hypermethylation, and impair differentiation in acute myeloid leukemia, showing that metabolic alterations can be causal rather than merely correlative." (PMID 41295305, 2025). "For anticancer drugs, ivosidenib and enasidenib were developed on the basis of oncometabolites, which inhibit mutated IDH1 and mutated IDH2, respectively, in acute myeloid leukemia (AML), thereby suppressing the biosynthesis of D-2-hydroxyglutarate." (PMID 38468344, 2024). "An IDH1 inhibitor, Ivosidenib (AG-120), has been approved for treating relapsed or refractory acute myeloid leukemia." (PMID 39156101, 2024). "IDH1 and IDH2 are recurrently mutated in myeloid neoplasms, including myelodysplastic syndrome (5%‒10%), acute myeloid leukemia (10%‒20%), and MPN (1%‒5%), as well as in lymphoma and some solid cancers." (PMID 39157630, 2024). "CIMP in leukemia is associated with distinct molecular features, including TET2, IDH1 and IDH2 mutations in acute myeloid leukemia." (PMID 37234978, 2023).
acute myeloid leukemia (continued). "Mutations in IDH1 and IDH2 genes lead to increased production of D-2 hydroxy-glutarate (2HG), contributing to the development of various malignancies such as acute myeloid leukemia, chondrosarcoma, cholangiocarcinoma, and glioma." (PMID 36902385, 2023). "IDH mutations were also found in 10–20% of patients with acute myeloid leukemia (AML), with a low incidence in other cancers; the majority of these lesions involve arginine (R) residue mutations in IDH1 codon 132 (IDH1 R132) and residues 140 and 172 of IDH2 (IDH2 R140 and IDH2 R172)." (PMID 35765075, 2022). "Isocitrate dehydrogenase (IDH) is an appealing target for anticancer therapy, and IDH (IDH1/2) inhibitors have been approved for targeted therapy of acute myeloid leukemia (AML) and Cholangiocarcinoma." (PMID 35526267, 2022). "IDH1/2 mutations are also present in hematological malignancies, mainly in acute myeloid leukemia (AML, ~ 20%), but also in myeloproliferative neoplasms (MPN, ~ 1–4%), in myelodysplastic syndromes (MDS, ~ 5%) and angioimmunoblastic T‐cell lymphomas (AITL, ~ 20–30%)." (PMID 36062346, 2022). "IDH1/IDH2 mutations are also present in other neoplasms, such as acute myeloid leukemia (AML), chondrosarcoma and cholangiocarcinoma." (PMID 36011350, 2022). "In low-grade glioma, secondary glioblastoma, and acute myelogenous leukemia, the oncogenic mutations in the two-isocitrate dehydrogenase (IDH) encoding genes (IDH1 and IDH2) have been identified." (PMID 36188571, 2022). "In acute myeloid leukemia (AML), the IDH1/2 and TET2 mutations repel each other." (PMID 36428791, 2022). "Heterozygous somatic mutations affecting IDH1/IDH2 genes and DNA methylation profiles have also been found in glioma and acute myeloid leukemia (AML)." (PMID 35269864, 2022). "Among its three isoforms, mutations in the IDH1 and IDH2 genes are found in the majority of low- and high-grade gliomas as well as in 20% of adults with acute myeloid leukemia (AML), and 5% of adults with myelodysplastic syndromes (MDSs)." (PMID 33673109, 2021). "Ivosidenib, an inhibitor of IDH1 mutants, and enasidenib, an inhibitor of IDH2 mutants, are reportedly effective against relapsed and refractory acute myeloid leukaemia (AML) with IDH1 and IDH2 mutations, respectively." (PMID 33562094, 2021). "Mutations in IDH1 and IDH2 genes have been described in several malignancies, including gliomas, acute myeloid leukemia (AML), and myelodysplastic disorders." (PMID 34069269, 2021). "Ivosidenib is an IDH1 inhibitor approved in the USA for patients with mutant IDH1 (mIDH1) acute myeloid leukaemia." (PMID 33451059, 2021). "Mutations in R132 and R172 in isocitrate dehydrogenase 1 and 2 (IDH1/2) have been found in approximately 20% of acute myeloid leukemias (patients with a devastating prognosis." (PMID 33785068, 2021). "IDH1 and IDH2 mutations cause global DNA hypermethylation because of decreased α-ketoglutarate levels and TET2 function in many cancer types, including acute myelogenous leukemia (AML)." (PMID 33868269, 2021). "IDH1 and IDH2 mutations are present across several cancers including in 5-16% and 6-19% of acute myeloid leukaemia (AML), respectively." (PMID 33391954, 2021). "Isocitrate dehydrogenase isoform-1 (IDH1) and 2 (IDH2) mutations are considered to be associated with HIF-α stability in solid tumors, notably glioblastoma and acute myeloid leukemia (AML)." (PMID 33109235, 2020). "Thus, various tumors, including glioma, secondary glioblastoma, and acute myeloid leukemia (AML), harboring heterozygous point mutations in the active sites of IDH1/2 show dramatic increases in the R-2-HG levels." (PMID 32943735, 2020). "Moreover, the driver mutations affecting isocitrate dehydrogenase (IDH)-1 and −2 genes are shown to result in accumulation of oncometabolite 2-hydroxyglutarate that has a prognostic value in acute myeloid leukemia (AML)." (PMID 32763516, 2020).
acute myeloid leukemia (continued). "Over the years, several molecules have been developed, able to selectively inhibit one of the different mutated IDH isoforms by reducing 2-HG levels and stimulating the differentiation of mutant IDH1/IDH2 acute myeloid leukemia (AML) cells." (PMID 32825551, 2020). "Mutations in IDH1 and IDH2 (Isocitrate dehydrogenase) genes are found in different cancers, including glioblastoma and acute myeloid leukemia (AML)." (PMID 32397535, 2020). "For example, the small molecule inhibitor ivosidenib, which targets IDH1 with a mutation at R132, has been approved by the FDA for the clinical treatment of acute myeloid leukemia." (PMID 30984620, 2019). "Instead, to counteract the aberrant DNA hypermethylation caused by 2-HG production in IDH1/2 mutant cancers, promising IDH1/2 mutant inhibitors are available, and Ivosidenib has been recently approved from FDA for acute myeloid leukemia." (PMID 31366176, 2019). "Driver mutations in IDH1 and IDH2 have been likewise identified in acute myeloid leukemia (AML), chondrosarcoma, myelodysplastic syndromes, and cholangiocarcinoma." (PMID 31165048, 2019). "An independent study demonstrated that high IDH1 expression was correlated to poor prognosis in cytogenetically normal acute myeloid leukemia patients." (PMID 31010244, 2019). "A study described that IDH1 silencing enhances the toxicity of the sensitizer rose bengal in the acute myeloid leukemia cell line HL-60, as a consequence of decreased NADPH and GSH levels, and increased ROS production." (PMID 31010244, 2019). "In the acute myeloid leukemia (LAML) cohort, 1.38% of missense mutations were in DNMT3A gene (p.R882H), 1.05% were IDH2 p.R140Q, and 0.79% were IDH1 p.R132C." (PMID 30890735, 2019). "IDH mutation occurs in 20% of acute myeloid leukemia (AML) patients, mainly including IDH1 R132, IDH2 R140, and IDH2 R172." (PMID 31660152, 2019). "Recently, a report showed that mutations of the isocitrate dehydrogenase (IDH) genes IDH1 and IDH2 can inactivate methylcytosine dioxygenase activity, resulting in DNA hypermethylation in acute myeloid leukemia cells." (PMID 31352437, 2019). "Mutations of the isocitrate dehydrogenase genes (IDH1 and IDH2) have been detected in several tumor types including chondrosarcoma, acute myeloid leukemia (AML), cholangiocarcinoma and diffuse glioma." (PMID 29499756, 2018). "IDH1 and IDH2 mutations have been identified in acute myelogenous leukemia, lymphoma, glioblastoma, chondrosarcoma and other solid tumours." (PMID 30356832, 2018). "In normal karyotype acute myeloid leukemia, the IDH1 (rs11554137) SNP was an adverse prognostic factor." (PMID 28218607, 2017). "For instance, glioblastoma or acute myeloid leukemia (AML) tumors that harbor IDH1/ IDH2 mutations are particularly dependent on the function of the GAC isoform for the anaplerotic replenishment of αKG, which is the source material used to generate the onco-metabolite 2-HG by these mutant enzymes." (PMID 28950000, 2017). "Moreover, in 20% of acute myeloid leukemia (AML), 50% of chondrosarcoma, 20% of intrahepatic cholangiocarcinoma, and 20% of angioimmunoblastic T-cell lymphoma, IDH1 or IDH2 are mutated as well." (PMID 27014623, 2016). "Somatic mutations in cytoplasmic IDH1 and mitochondrial IDH2 are common early drivers in glioma and acute myeloid leukaemia (AML), being most frequent in diffuse gliomas and secondary glioblastoma." (PMID 27803395, 2016). "Isocitrate dehydrogenase 1 (IDH1), and IDH2 mutations were originally reported as frequent events in gliomas and acute myeloid leukaemia." (PMID 25432631, 2015). "The extent of intron retention correlated with the presence of IDH1 and IDH2 mutations in acute myeloid leukemia and across molecular subtypes in breast cancer." (PMID 26113877, 2015). "The isocitrate dehydrogenase (IDH1/IDH2) genes are metabolic enzymes, which are frequently mutated in acute myeloid leukemia (AML)." (PMID 25324972, 2014).
acute myeloid leukemia (continued). "IDH1/2 mutations are also common in hematopoietic malignancies, including acute myeloid leukemia (AML), myelodysplastic syndromes (MDS), myeloproliferative neoplasms and T-cell lymphomas, as well as in solid tumors such as chondrosarcoma and cholangiocarcinoma." (PMID 25473433, 2014). "Mutations in epigenetic modifiers were reported in patients with acute myeloid leukaemia (AML) including mutations in DNA methyltransferase 3A gene (DNMT3A) in 20%-30% patients and mutations in isocitrate dehydrogenase 1/2 gene (IDH1/2) in 5%-15% patients." (PMID 24887327, 2014). "Acquired somatic mutations of IDH1 and IDH2 have recently been reported in some types of brain tumors and a small proportion of acute myeloid leukemia (AML) cases." (PMID 22397365, 2012). "Gain-of-function mutations and decreased expression of IDH1 have been demonstrated to be associated with pathogenesis of various myeloid malignancies characterized by ineffective erythropoiesis, such as acute myeloid leukemia (AML) and myelodysplastic syndrome (MDS)." (PMID 40299922, 2025). "In fact, the widespread occurrence of IDH1/IDH2 mutations in gliomas and acute myeloid leukemia has led to the successful development of FDA approved IDH inhibitors, which are now used in combination therapies to treat IDH1/IDH2-positive tumors." (PMID 40236175, 2025). "Nat Commun 2022; 13:4785.○ This reference is of outstanding importance because it describes the binding properties and inhibitor activity of IDH1 inhibitors such as olutasidenib and ivosidenib against single mutant and double mutant IDH1 acute myeloid leukemia cells." (PMID 39406957, 2024). "Furthermore, in acute myeloid leukemia, CIMP can be further divided into two categories, I-CIMP associated with IDH1/2 mutations and A-CIMP enriched in CEBPA and WT1 mutations." (PMID 37234978, 2023). "Hotspot mutations of IDH1/2 have been identified in various human malignancies, including diffuse gliomas, myelodysplastic syndrome (MDS), chondrosarcoma, intrahepatic cholangiocarcinoma (ICC), and acute myeloid leukemia (AML)." (PMID 37108511, 2023). "The role of allogeneic hematopoietic cell transplantation (alloHCT) in acute myeloid leukemia (AML) with mutated IDH1/2 has not been defined." (PMID 36064577, 2022). "While acute myeloid leukemia (AML) is still associated with a low cure rate, recent advances in understanding its molecular complexity have significantly improved therapy for subgroups of patients, including those harboring FLT3, IDH1, or IDH2 mutations." (PMID 35354920, 2022). "Three drugs, based on targeting asparagine metabolism in acute lymphoid leukemia and mutant IDH1/2 in acute myeloid leukemia, have received approval from the U.S. Food and Drug Administration (FDA), and many others are under development either in preclinical or clinical studies." (PMID 35054987, 2022). "Ivosidenib was selected for downstream experiments since this drug performed well compared with other tested compounds, is well tolerated in patients and is already FDA approved for medically refractory IDH1-mutant acute myeloid leukemia and IDH1-mutant cholangiocarcinoma." (PMID 35681100, 2022). "Serum 2-HG in IDH1-mutated and IDH2-mutated cancers like acute myeloid leukemia is about 300 μM44." (PMID 34131130, 2021). "Consistent with this notion, the mutant IDH1 (ivosidenib) and IDH2 (enasidenib) protein inhibitors have been initially approved by the U.S. food and drug administration (FDA) for relapsed/refractory acute myeloid leukemia (AML)-bearing IDH1 and IDH2 mutations." (PMID 35996504, 2021).
acute myeloid leukemia (continued). "In addition, in patients with acute myelocytic leukemia, the overexpression of IGF2BP2 indicates poor survival, and IGF2BP2 expression is associated with mutations in FLT3-ITD and IDH1, which are also indicators of poor prognosis." (PMID 33628845, 2021). "Interestingly, the frequency of IDH1/2 mutation was relatively high in acute myeloid leukemia (AML) and glioma; this suggests that tumor cells with these kinds of mutations may be well response to proferroptotic therapy." (PMID 33425217, 2020). "Interestingly, gain-of-function mutations of the enzymes responsible for 2-oxoglutarate synthesis, IDH1 and IDH2, have been associated with tumorigenesis, in particular glioblastomata and acute myeloid leukemia." (PMID 25568311, 2015). "IDH1 and IDH2 mutations widely occur in gliomas and acute myeloid leukemia, leading to the production of 2-hydroxyglutarate (2-HG), which inhibits multiple α-KG-dependent dioxygenases, including the TET family of 5-mC hydroxylases (which results in decreased 5-hmC)." (PMID 24716838, 2014). "The development of targeted treatments, including inhibitors of BCL-2, FLT3, IDH1/2, and menin, has significantly expanded the therapeutic landscape of acute myeloid leukemia (AML), offering more personalized and molecularly driven treatment approaches." (PMID 41899095, 2026). "In isocitrate dehydrogenase 1 (IDH1)-mutant Acute Myeloid Leukemia (AML), the combination of Ivosidenib with the hypomethylating agent azacitidine, significantly improved clinical outcomes compared to monotherapy." (PMID 40573249, 2025). "Hotspot mutations in IDH1 and IDH2 occur in various human cancers, including GBM, acute myeloid leukemia (AML), and cholangiocarcinoma." (PMID 40563819, 2025). "PARP inhibitors (PARPi) have shown promise in treating acute myeloid leukemia (AML) and other blood cancers, particularly in cases with specific genetic alterations such as RUNX1-RUNX1T1, PML-RARA, FLT3, and IDH1/2 mutations." (PMID 41048997, 2025). "In humans, IDH1 and IDH2 mutations are frequently observed in cancers such as gliomas and acute myeloid leukemia (AML)." (PMID 39941051, 2025). "Olutasidenib is a potent, selective, oral, small-molecule inhibitor of mutant isocitrate dehydrogenase 1 (IDH1) that was recently approved by the US FDA for adult patients with relapsed or refractory acute myeloid leukemia (AML) harboring mutant IDH1." (PMID 40594997, 2025). "The combination of ivosidenib—an IDH1 inhibitor—and azacitidine has been approved by the FDA for the treatment of older adults with newly diagnosed IDH1-mutated acute myeloid leukemia (AML)." (PMID 41236698, 2025). "Mutations in IDH1 or IDH2, present in ∼15–20% of acute myeloid leukemia (AML) cases, generate the oncometabolite (R)-2-hydroxyglutarate (2-HG), enforcing a hypermethylated, differentiation-refractory state." (PMID 41347170, 2025). "Non-driver mutations, such as those in ASXL1, EZH2, TET2, SRSF2, and IDH1/IDH2, have been found to exacerbate disease severity, accelerate progression, and increase the risk of transformation to acute myeloid leukemia (AML)." (PMID 39434124, 2024). "The gain-of-function mutations of IDH1 and IDH2 genes commonly occur in GBM and acute myeloid leukemia (AML) and are associated with accelerated tumor cell proliferation and inhibited differentiation." (PMID 39199642, 2024). "Ivosidenibis an isocitrate dehydrogenase-1 (IDH1) inhibitor and was recentlyapproved for the treatment of acute myeloid leukemia (AML)." (PMID 35881912, 2023). "IDH inhibitors are another type of targeted therapy that target genetic mutations in the isocitrate dehydrogenase genes (IDH1 and IDH2) in acute myeloid leukemia (AML), occurring in up to 30% of AML cases." (PMID 37374055, 2023).